AGBL4 (AGBL carboxypeptidase 4)
Description:
Metallocarboxypeptidase that mediates protein deglutamylation of tubulin and non-tubulin target proteins. Catalyzes the removal of polyglutamate side chains present on the gamma-carboxyl group of glutamate residues within the C-terminal tail of tubulin protein. Specifically cleaves tubulin long-side-chains, while it is not able to remove the branching point glutamate. Also catalyzes the removal of polyglutamate residues from the carboxy-terminus of non-tubulin proteins such as MYLK. Mediates the deglutamylation of nucleotidyltransferase CGAS, leading to CGAS antiviral defense response activation (By similarity). Involved in KLF4 deglutamylation which promotes KLF4 proteasome-mediated degradation, thereby negatively regulating cell pluripotency maintenance and embryogenesis.
Synonyms: CCP6; FLJ14442
Tractability: No criterion of Open Targets' tractability assessment is met for any kind of drug.
Target class: Enzyme; Hydrolase
Safety:
Unwanted effects reported when the protein is acted on. In parentheses: how it was acted on, where the effect was seen, and who reports it.
liver toxicity (source: ClinPGx)
Gene: Protein-coding gene on chromosome 1 (48,532,854 to 50,023,954, reverse strand). Ensembl gene ENSG00000186094.
Subcellular location: Cytoplasm, cytosol; Cytoplasm, cytoskeleton, microtubule organizing center, centrosome, centriole; Golgi apparatus; Cytoplasm, cytoskeleton, cilium basal body
Pathways (Reactome):
Metabolism of proteins: Carboxyterminal post-translational modifications of tubulin
Gene Ontology:
Molecular function: metallocarboxypeptidase activity; tubulin binding; zinc ion binding
Biological process: defense response to virus; proteolysis
Cellular component: centriole; ciliary basal body; Golgi apparatus; cytoplasm; cytosol; microtubule cytoskeleton
Genetic constraint (gnomAD): Loss-of-function variants: 49 observed, 56.15 expected, observed/expected ratio (o/e) 0.87, 90% interval 0.69 to 1.11. The upper end of that interval is the gene's LOEUF score, 1.11, which puts it in group 4 of 6, group 1 being the genes least tolerant of losing a copy. Missense variants: 554 observed, 593.08 expected, observed/expected ratio (o/e) 0.93, 90% interval 0.87 to 1. Synonymous variants: 230 observed, 211.16 expected, observed/expected ratio (o/e) 1.09, 90% interval 0.98 to 1.22.
Homologues: Orthologues: chimpanzee AGBL4 (99% identical), guinea pig AGBL4 (87% identical), mouse Agbl4 (86% identical), macaque BEND5 (73% identical), Drosophila melanogaster CG31019 (46% identical), Caenorhabditis elegans ccpp-6 (43% identical), zebrafish AGBL4 (27% identical). Paralogues in human: AGTPBP1 (32% identical), AGBL2 (31% identical), AGBL1 (31% identical), AGBL3 (30% identical), AGBL5 (28% identical).
Diseases named in the same sentence as AGBL4 in open-access papers:
AGBL4 is named in the same sentence as 27 diseases in open-access papers, as found by Europe PMC text mining. Sharing a sentence is not in itself a finding about the gene and the disease. The quoted sentences say what the papers report.
ischemic stroke (2 papers, 2017 to 2023). A stroke disorder caused by obstruction of blood flow to the brain, due to thrombotic (local blood clot formation) or embolic (due to a blood clot or other material traveling from another site) event. "Change in cognitive functioning over 10 years was associated with DNA methylation levels in AGBL4 (p = 9.01 × 10−7) and SORBS1 (p = 5.28 × 10−6), with the first gene playing an important role in neuronal survival and the latter gene implicated before in Alzheimer's disease and ischemic stroke." (PMID 29311901, 2017).
male infertility (2 papers, 2021 to 2022). The inability of the male to effect fertilization of an ovum after a specified period of unprotected intercourse. "However, no study has yet reported that this gene is associated with male infertility, and there is only a patent indicating that AGBL4 is one of the candidate genes for male infertility." (PMID 33819193, 2021). "Hence, more studies are needed to further validate the role of AGBL4 in male infertility." (PMID 33819193, 2021).
neuroblastoma (2 papers, 2021 to 2024). Neuroblastoma (NB) is the most common solid, extracranial childhood tumor. "AGBL4, encoding a cytosolic carboxypeptidase, has a potential role in neuroblastoma, autism and developmental delay." (PMID 34556655, 2021). "We investigated the effects of TIR on markers of neuronal growth (CREB and BDNF), apoptosis (BAX/Bcl2 ratio) differentiation (pAkt, MAP2, GAP43, and AGBL4), and insulin resistance (GLUT1, GLUT4, GLUT3 and SORBS1) in a neuroblastoma cell line (SHSY5Y) exposed to normal and high glucose concentration." (PMID 38287296, 2024).
teratozoospermia (2 papers, 2021 to 2022). "Ultimately, we screened to obtain three potential biomarker genes with the highest differential expression in the teratozoospermia group of patients, AGBL4, FAM172A and RUNDC3B." (PMID 33819193, 2021).
cardiofaciocutaneous syndrome 2 (1 paper, 2021). Any cardiofaciocutaneous syndrome in which the cause of the disease is a mutation in the KRAS gene. "Both Cardiofaciocutaneous Syndrome 3 and Cardiofaciocutaneous Syndrome 2 have been shown to be associated with the AGBL4 gene." (PMID 33819193, 2021).
cataract (1 paper, 2022). Partial or complete opacity of the crystalline lens of one or both eyes that decreases visual acuity and eventually results in blindness. "Particularly, mutations in three of them, AGBL4, DYNC2H1, and KIZ, cause retinal pathologies in humans, while a NID1 mutation was found to be the cause of the development of recessive cataracts in Romagnola cattle." (PMID 36669004, 2022).
colorectal cancer (1 paper, 2024). A primary or metastatic malignant neoplasm that affects the colon or rectum. "Emerging evidence implicates the ATP/GTP-binding protein-like 4 gene (AGBL4) in various pathological processes, including antituberculosis drug-induced hepatotoxicity, cardiometabolic risk, and colorectal cancer, where it is anticipated to serve as a novel biomarker." (PMID 39007144, 2024).
glioma (1 paper, 2024). A benign or malignant brain and spinal cord tumor that arises from glial cells (astrocytes, oligodendrocytes, ependymal cells). "Transcriptomic and bioinformatic analyses further revealed that AGBL4-realted DEGs were enriched in cancer-associated microRNA-related pathways and IL-17 signaling pathway, the latter being notably related to malignancy in central nervous system tumors." (PMID 39007144, 2024). "Our study not only confirms the upregulation of MMP-1 in high-grade gliomas but also identifies AGBL4 as a novel upstream regulator of MMP-1." (PMID 39007144, 2024). "This groundbreaking research links AGBL4 to the aggressive nature of central nervous system tumors at the molecular level for the first time." (PMID 39007144, 2024). "Furthermore, KEGG enrichment analysis suggested that AGBL4-associated DEGs might participate in pathways related to microRNAs in human cancer and contribute to the IL-17 signaling pathway, which is frequently recognized as a reference index to judge the malignancy of gliomas." (PMID 39007144, 2024).
Obesity (1 paper, 2020). Accumulation of substantial excess body fat. "In addition, in this analysis, a few other regions emerged: a large region on SSC6 that encompasses the AGBL4 gene, which is involved in obesity and fat deposition traits, and a few other regions on SSC15, including a region close to the previously reported CASP10 gene." (PMID 32591011, 2020).
prostate carcinoma (1 paper, 2014). A carcinoma that arises from epithelial cells of the prostate gland. "The model was able to identify prostate cancer associated SNPs that either map to a cancer specific genes such as CRR9, TERT, ATP2B2, ARL9, and AGBL4 and/or with regulatory effects." (PMID 24651484, 2014).
sarcoidosis (1 paper, 2024). Sarcoidosis is a multisystemic disorder of unknown cause characterized by the formation of immune granulomas in involved organs. "Our integrated model also demonstrated differential expression/methylation of IL20RB, ABCC11, SFSWAP, AGBL4, miR-146a-3p, and miR-378b between non-progressive and progressive sarcoidosis." (PMID 39080656, 2024).
tumour (3 papers, 2015 to 2024). "AGBL4 expression was observed across a majority of these tumor clusters, with a significant upregulation in recurrent GBM compared to primary GBM." (PMID 39007144, 2024). "This suggests a possible link between AGBL4’s oncogenic effects and inflammatory pathways, highlighting its role in the tumor microenvironment’s immune responses." (PMID 39007144, 2024). "The upregulation of MMP-1, mediated by AGBL4, may not only promote tumor invasiveness through structural modifications but could also exacerbate inflammation, thereby creating a more conducive environment for tumor growth and spread." (PMID 39007144, 2024). "Based on these findings, we speculated that AGBL4-related DEGs might play significant roles in tumor progression within the central nervous system." (PMID 39007144, 2024). "Further, our experimental findings underscore the critical role of AGBL4 in tumor biology, revealing that knocking down AGBL4 inhibits the proliferation, migration, and invasion of GBM cells, thertby highlighting its importance in tumor viability and progression." (PMID 39007144, 2024). "RT-PCR analysis revealed that among these candidates, MMP-1 exhibited the most significant differential expression, identifying it as a target for further investigation to clarify the specific signaling pathway through which AGBL4 may promote GBM tumor progression." (PMID 39007144, 2024). "In summary, this study demonstrates that AGBL4 expression in GBM is upregulated and links with poor prognosis of GBM patients by enhancing tumor cell proliferation, migration, and invasion." (PMID 39007144, 2024). "Subsequent analyses showed a complex relationship among AGBL4, MMP-1, and other inflammatory genes in regulating the GBM tumor microenvironment, affecting tumor behavior and patient survival." (PMID 39007144, 2024). "Our findings reveal a novel mechanistic pathway where AGBL4 enhances GBM malignancy primarily through modulation of MMP-1 expression, which in turn influences the inflammatory response pathways within the tumor microenvironment." (PMID 39007144, 2024). "In addition, the interaction between AGBL4 and MMP-1 highlights a potential connection to the inflammatory processes within the tumor microenvironment of GBM." (PMID 39007144, 2024). "AGBL4, ROBO2, EYS and RYR3 appeared to have two insertions in distinct sites in the same tumour, though these could be insertions at a single rearrangement junction, since this is known to occur." (PMID 26159513, 2015).
AGBL4 also shares sentences with these, for which no sentence is quoted: cancer (4 papers); infection (2); Alzheimer disease (1); autism (1); Azoospermia (1); cardiofaciocutaneous syndrome 3 (1); ciliopathy (1); developmental delay (1); glioblastoma (1); Joubert syndrome (1); kidney stones (1); leukemia (1); renal adenocarcinoma (1); renal cell carcinoma (1); schizophrenia (1).